HMGB1 (high mobility group box 1)
Diseases named in the same sentence as HMGB1 in open-access papers (continued):
Sharing a sentence is not in itself a finding about the gene and the disease.
Sepsis (continued). "The administration of IDC-derived exosome containing MFG-E8 significantly suppressed the expression of proinflammatory cytokines, including TNF-α, IL-6, and High Mobility Group Box 1 (HMGB1), in CLP sepsis animals." (PMID 27429513, 2016). "Naringin protected mice from CLP-induced sepsis in an HO-1-dependent manner by reducing serum TNF-α and HMGB1 levels." (PMID 27716835, 2016). "These CKD-sepsis models showed remarkably high mortality with increased blood levels of vascular endothelial growth factor (VEGF) and HMGB1." (PMID 27011788, 2016). "Taken together, pre-existing renal injury amplifies sepsis disease progression and sepsis-induced AKI by increasing VEGF and HMGB1." (PMID 27011788, 2016). "Moreover, High-mobility group box 1 (HMGB1), a cytokine mediator of lethal systemic inflammation in sepsis and non-sepsis diseases, has been implicated in heatstroke-induced SIRS and direct inhibition of HMGB1 with its monoclonal antibody can decrease circulating inflammatory cytokines." (PMID 25653103, 2015). "Sepsis is mediated by early (tumor necrosis factor-α (TNF-α), interleukin-6 (IL-6)) and late (high mobility group box-1 (HMGB1)) inflammatory cytokines in response to infection." (PMID 25930108, 2015). "Sepsis is a potentially fatal syndrome mediated by an early [e.g., tumor necrosis factor-alpha (TNF-α)] and late [high mobility group box-1 (HMGB-1)] proinflammatory cytokine response to infection." (PMID 26579229, 2015). "Given the capacity of various herbal components in preventing endotoxin-induced HMGB1 secretion, we explored their efficacy in animal models of CLP-induced sepsis." (PMID 25821489, 2015). "Some studies indicate that RAGE is the major receptor for the proinflammatory activity of HMGB1 and RAGE activation through HMGB1 has been involved in mediating sepsis." (PMID 25821501, 2015). "Anti-HMGB1 antibodies ameliorated the severity of sepsis in a cecal ligation and puncture (CLP)-induced polymicrobial sepsis model in rat." (PMID 25722880, 2015). "Given that various herbal components are capable of preventing endotoxin-induced HMGB1 secretion, we explored their efficacy in animal models of CLP-induced sepsis." (PMID 26257917, 2015). "Recent investigations have demonstrated that HMGB1 and its pertinent receptor-RAGE have increasingly become important prognostic indices and potential therapeutic targets in the development of sepsis-induced lung injury." (PMID 25821501, 2015). "Moreover, the targeted inhibition of HMGB1 expression in innate immune cells (e.g., macrophages and dendritic cells) reduces systemic HMGB1 accumulation and similarly rescues mice from sepsis, supporting HMGB1 as a critical late mediator of experimental sepsis." (PMID 26257917, 2015). "The ways of signal transduction of immune activation seem to be identical in sepsis and SIRS, involving complex interaction of the DAMP HMGB1 with surface receptors, leading to long-term maintenance of immune response." (PMID 26854151, 2015). "C5L2 has been shown to play a proinflammatory role during sepsis through intracellular signaling, release of cytokines IL-6, tumor necrosis factor α (TNF-α), and high mobility group box 1(HMGB1)." (PMID 24740152, 2014). "Similar to HMGB1, large amounts of MIF are released during sepsis, which promotes a pro-inflammatory response by amplifying cytokine secretion through the upregulation of TLR4 expression." (PMID 25870671, 2014). "High mobility group box 1 (HMGB1) is the ligand of RAGE, and has been recently identified as a lethal mediator of severe sepsis." (PMID 24065095, 2013). "We showed that THI-56 significantly inhibits HMGB1 release, both in vitro and in in vivo sepsis models, indicating that THI-56 is a potential candidate for the treatment of sepsis." (PMID 24098466, 2013). "Previous studies have shown that HMGB-1 differs from early innate proinflammatory cytokines, such as TNF and IL-1, in endotoxaemia and sepsis models." (PMID 24188108, 2013).
Sepsis (continued). "High mobility group box 1 (HMGB1), a nuclear protein widely studied as a transcription factor and growth factor, has recently been identified as a critical mediator of severe sepsis." (PMID 24371375, 2013). "More recently, the increased release of high-mobility group box protein 1 (HMGB1) and splenic apoptosis in septic CKD mice has highlighted these pathways in the CKD/sepsis interaction." (PMID 23548034, 2013). "Recently, it has been demonstrated that a ubiquitous protein, high mobility group box 1 (HMGB1), is released by activated macrophages/monocytes and functions as a late mediator of lethal endotoxemia and sepsis." (PMID 24098466, 2013). "Peroxisome proliferator-activated receptors (PPARs) are shown to modulate the pathological status of sepsis by regulating the release of high mobility group box 1 (HMGB1), a well-known late proinflammatory mediator of sepsis." (PMID 23316104, 2012). "HMGB-1, sRAGE and RAGE have been involved in sepsis and their potential as severity markers has been proposed." (PMID 22264245, 2012). "Ethyl pyruvate, an anti-oxidant that inhibits HMGB1 secretion from macrophages, can be added a day after TNF production to reverse the established sepsis." (PMID 20628562, 2010). "The present study is the first report on the implications of the genetic variation in the human HMGB1 gene in a population of critically ill patients admitted to an ICU with SIRS and sepsis." (PMID 18577209, 2008). "We recently discovered that a ubiquitous protein, high mobility group box 1 (HMGB1), is released by activated macrophages/monocytes, and functions as a late mediator of lethal endotoxemia and sepsis." (PMID 17987129, 2007). "The pathogenesis of lethal sepsis remains obscure, but is mediated in part by excessive release of early (e.g., TNF and IL-1) and late (e.g., HMGB1) proinflammatory cytokines." (PMID 17987129, 2007). "The aim of the present study was to investigate levels of HMGB1, LBP and PCT in a well-characterised sepsis cohort." (PMID 17625012, 2007). "The present study purpose was to examine levels of HMGB1, LBP and PCT in patients with sepsis of different severity, in bacteraemic patients and in relation to the outcome of the patients." (PMID 17625012, 2007). "Levels of HMGB1, LBP and PCT were higher in the severe sepsis group compared with the sepsis group (P < 0.01)." (PMID 17625012, 2007). "Unlike early inflammatory mediators, such as TNF‐a, HMGB1 is considered to be a late mediator contributing to lethal systemic inflammation within cytokine‐mediated sepsis animal models." (PMID 41551210, 2026). "No statistically significant changes in HMGB1 protein levels were observed in rats with LPS-induced sepsis, regardless of pretreatment." (PMID 40371344, 2025). "Notably, lactate promotes macrophage HMGB1 lactylation in polymicrobial sepsis, inducing endothelial dysfunction (an important indicator in AAA) through the secretion of HMGB1 via exosomes." (PMID 41213933, 2025). "Our findings align with this paradigm: recombinant HMGB1 stimulation of RAW 264.7 macrophages markedly induced these NF-κB target genes and cytokines, modeling the sustained inflammatory response observed in systemic inflammation and sepsis." (PMID 41226481, 2025). "Furthermore, in a sepsis model, macrophages uptake lactate through MCT, driving lactylation modification on high mobility group box 1 (HMGB1), thereby promoting disease progression." (PMID 40589733, 2025). "Therefore, endothelial GSDMD mediates the regulatory effects of the HMGB1/RAGE axis on vascular injury and death in sepsis." (PMID 39927458, 2025). "In a previous study, treatment with AIM in sepsis showed a negative correlation with protein levels of HMGB1, another prominent DAMP." (PMID 41162904, 2025). "Another diagnostic and monitoring marker of sepsis, not commonly analyzed in septic patients, is the late pro-inflammatory cytokine and alarmin HMGB1 (high mobility group box 1)." (PMID 41153764, 2025).
Sepsis (continued). "Platelets generated from sepsis-reprogrammed MKs exhibit increased “immune” phenotypes, release CD40L and high mobility group box 1 (HMGB1), which promote neutrophil extracellular traps (NET) formation, further contributing to immunothrombosis and microvascular injury." (PMID 41303674, 2025). "Uncontrolled inflammation in sepsis results in an increase in the release of pro-inflammatory cytokines, including tumor necrosis factor alpha (TNF-α), interleukin-1 beta (IL1-β), IL-6, and HMGB-1." (PMID 39838305, 2025). "Therapeutic options to regulate HMGB1 in preclinical models are being evaluated in the field of non-neoplastic diseases (sepsis, inflammation), as well as in cancer." (PMID 40804938, 2025). "In sepsis, lipopolysaccharide, a cell wall component of Gram-negative bacteria, stimulates macrophages, leading to the release of HMGB1, an important inflammatory mediator." (PMID 40688353, 2025). "As a critical PRR in sepsis, TLR4 recognizes several DAMPs, such as eCIRP, HMGB1, and histones." (PMID 40421030, 2025). "Furthermore, GSDMD targeting the ER is responsible for calcium leakage, which in turn facilitates the translocation of HMGB1 from the nucleus to the cytosol, rendering this DAMP available for release in sepsis." (PMID 40783818, 2025). "Other authors have explored the ability of PMX to reduce HMGB1 in sepsis but, again, the effects on the outcome have not been investigated." (PMID 38256033, 2024). "Although HMGB1 is not yet included in standard sepsis guidelines, research on its utility as a biomarker is ongoing." (PMID 39201697, 2024). "While research on histone lactylation is more prevalent, beyond the investigation of nonhistone Fis1 lactylation, macrophage-derived nonhistone HMGB1 lactylation in sepsis has also been reported." (PMID 39234245, 2024). "The downregulation of HMGB1-induced barrier integrity reduction, leakage, and phosphorylated p38 suggests that CGK012 may be a promising molecule for the treatment of sepsis." (PMID 38474222, 2024). "HMGB1 has been known to induce the production of cytokines like TNF-α, IL-1β, and IL-6 through various mechanisms, including the NF-κB and ERK 1/2 pathways, exacerbating the pathological condition of sepsis." (PMID 38474222, 2024). "As a late inflammatory mediator, HMGB1 binds to TLR4 and receptor for advanced glycation end-products (RAGE) on neutrophils and macrophages to induce NETs production and cytokine/chemokine release, playing a damaging role in sepsis." (PMID 39712008, 2024). "Pharmacological inhibition of HMGB1 with neutralizing antibodies conferred protection against lethal sepsis, even when administered 24 hours post-CLP, establishing HMGB1 as a “late” mediator of sepsis with a broader therapeutic window." (PMID 39763679, 2024). "In another experiment, nicotine inhibited the release of HMGB1 from macrophages induced by endotoxin or TNF-α by activating cholinergic signaling pathways, prevented NF-κB pathway activation, and improved the survival rate in experimental models of sepsis." (PMID 39206262, 2024). "Sepsis diagnosis is based on the presence of certain biomarkers in the patient’s blood, for instance, C-reactive protein (CRP), procalcitonin (PCT), tumor necrosis factor-alpha (TNF-α), high-mobility group box 1 protein (HMGB-1), and interleukin-6 (IL-6)." (PMID 38920613, 2024). "It is noteworthy that we and others have reported that lactate can promote the lactylation of non-histone proteins, such as high mobility group box 1 (HMGB1) and Snail1, in sepsis and other disease states." (PMID 39372401, 2024). "In summary, these findings demonstrate that YTHDF2 plays an essential role as an inhibitor of inflammation to reduce the release of HMGB1 by inhibiting the IL-6R/JAK2/STAT1 pathway, indicating that YTHDF2 is a novel target for therapeutic interventions in sepsis." (PMID 38026444, 2023).
Sepsis (continued). "miR-22 can inhibit the inflammatory response, target the HMGB1, and inhibit the HMGB1/TLR4/NF-kB pathway, to attenuate the sepsis-induced AKI, which indicates that miR-22 may serve as a potential treatment target in sepsis-induced AKI." (PMID 35960478, 2023). "In addition, miR-22 attenuated sepsis-induced rat AKI, targeting High Mobility Group Box 1 (HMGB1) and inhibiting the HMGB1/TLR4/NF-kB pathway." (PMID 37761260, 2023). "Additionally, we highlight important targets involved in sepsis‐related regulatory mechanisms, including GSDMD, HMGB1, STING, and SQSTM1, among others." (PMID 38020710, 2023). "Overexpression of miR-22 could target and suppress the expression of HMGB1, inhibit the release of inflammatory factors and the expression of HMGB1/TLR4/NF-κB signaling pathway-related proteins, to attenuate the sepsis-induced AKI." (PMID 35960478, 2023). "Moreover, it was demonstrated that NET-derived HMGB1 induces macrophage pyroptosis and IL-1β release via RAGE in a mouse model of sepsis." (PMID 36776857, 2023). "Our findings demonstrate that YTHDF2 plays an essential role as an inhibitor of inflammation by reducing the release of HMGB1 via inhibition of IL-6R/JAK2/STAT1 signalling, indicating that this pathway may be a novel therapeutic strategy for sepsis." (PMID 38026444, 2023). "In vitro, HMGB1 stimulates TF expression and release, contributing to sepsis induced by gram-negative bacteria after LPS linkage." (PMID 36835934, 2023). "In a sepsis model, CGA also protects mice from sepsis by blocking the release of HMGB1." (PMID 36856879, 2023). "The elevation of plasma HMGB1 is delayed but prolonged in septic mice, which can be observed from 8 to 32 h after LPS (i.p.)injection and from 18 to 72 h after cecal ligation and puncture (CLP) induced sepsis." (PMID 36865384, 2023). "NLRP3 inflammasome assembly and activation can self‐cleavage to produce an active form of Caspase‐1 (pro‐Caspase‐1), promoting the release of proinflammatory cytokines including IL‐1β, IL‐18, and the alarmin high mobility group protein B1 (HMGB1), en route to inflammation of sepsis." (PMID 37206244, 2023). "Our results indicate that YTHDF2 plays an anti-inflammatory role by reducing the release of HMGB1 via inhibition of the IL-6R/JAK2/STAT1 pathway, demonstrating that targeting YTHDF2 may constitute a promising approach to sepsis treatment." (PMID 38026444, 2023). "Consequently, HMGB1 has been characterized as a late-acting DAMP and mediator of lethal sepsis with a relatively wider therapeutic window than early proinflammatory cytokines." (PMID 36735789, 2023). "By increasing the non-toxic ApoA-I/LPS complex, the HS 18-mer reduces LPS/HMGB1-induced inflammation in sepsis." (PMID 36865384, 2023). "Notably, the expression level of HMGB1 in the BALF reached a high level at 24 h; this finding was consistent with the result of a previous study in a sepsis-induced ARDS model." (PMID 35392093, 2022). "Unlike early septic mediators, HMGB1 remains stable and at a high level in the bloodstream for 1–1.5 days in animal models of sepsis." (PMID 35216180, 2022). "A prospective study evaluated IL-6, HMGB-1, and neutrophil gelatinase-associated lipocalin (NGAL) in 14 septic patients and 16 patients without sepsis admitted to the ICU." (PMID 34991675, 2022). "In sepsis mice model induced by CLP, HMGB1 might promote the pyroptosis of liver macrophages and mediate the acute liver injury of sepsis." (PMID 35720285, 2022). "Further HIF-1α expression (p = 0.046) was found to decrease in sepsis; however, HMGB1 was decreased but not significant in sepsis compared to w/o sepsis patients." (PMID 35681439, 2022). "In the same vein, this study also showed that plasma RIPK3, MLKL, and HMGB1 levels were significantly higher in non-survivors than in survivors among critically ill patients with sepsis." (PMID 36289650, 2022).
Sepsis (continued). "A study showed that activation of α7nAChR and subsequent cholinergic anti-inflammatory signaling inhibited NF-κB nuclear translocation into macrophages, hence inhibiting the secretion of high mobility group box 1 (HMGB1), an important pro-inflammatory factors and mediator of advanced sepsis." (PMID 35812436, 2022). "In patients with sepsis, IL-6 decreased levels were associated with ICU survival; NGAL levels rose in non-survivors, while HMGB-1 levels were unchanged in both survivors and non-survivors regardless of complications." (PMID 34991675, 2022). "miR-103a-3p alleviates LPS-induced sepsis and MODS in vitro by decreasing HMGB1." (PMID 35720285, 2022). "However, the serum HMGB1 levels in sham, CLP sepsis, Lac + sham, and Lac + CLP sepsis were significantly reduced by 36.8, 49.3, 48.2, and 44.0%, respectively after depletion of serum exosomes." (PMID 34363018, 2022). "By contrast, HMGB1 expression in LPS-stimulated RAW264.7 cells was increased following transfection with miR−205−5b inhibitor, which indicated that miR-205−5b inhibited HMGB1 expression in LPS-induced sepsis." (PMID 35720285, 2022). "salidroside protects against sepsis-induced ALI and mortality, which might be through the HMGB1 nucleocytoplasmic translocation." (PMID 35720285, 2022). "High mobility group box 1 (HMGB1), a non-histone chromosomal protein, is released by macrophages during sepsis where it is thought with an emerging role in the development of thrombosis, to act as a pro-inflammatory cytokine." (PMID 35431977, 2022). "Cel inhibits inflammation and the Warburg effect in sepsis via targeting PKM2 and HMGB1 protein." (PMID 35596191, 2022). "Sepsis has a biphasic inflammatory process: producing pro-inflammatory cytokines in the early phase, including TNF and interleukins, and the late phase is mediated by HMGB1." (PMID 36081910, 2022). "In addition, sepsis increases the concentration of inflammatory factors (such as IL-6, TNF-α, HMGB1), which are the main inducers of apoptosis." (PMID 34057015, 2021). "Given that our knowledge on the origin of HMGB1 in sepsis is limited, we are not able to draw inferences with certainty at this time." (PMID 33947887, 2021). "However, brain HMGB1 translocates into the cytoplasm and occurs as a paracrine extracellular DAMP mediator during the cecal ligation and puncture model of sepsis, ischemia, seizure models, and hemorrhagic or traumatic brain injury." (PMID 34208101, 2021). "LPS stimulated hepatocyte release of HMGB1, while caspase-11 dependent does not lead to the induction of cell death in hepatocytes themselves, but drives immune cell pyroptosis during sepsis." (PMID 33546173, 2021). "Since the molecular mechanisms of inflammatory sepsis-inducedcardiac injury are not fully understood and considering the HMGB1/RAGE axis as animportant target of inflammatory disorder, the present study was aimed to identifythe role HMGB1/RAGE axis in sepsis-induced myocardial injury." (PMID 33605309, 2021). "Stimulated peripheral blood mononuclear cells (PBMCs) with or without lipopolysaccharides (LPS) and high-mobility group box 1 (HMGB1) were cultured with or without TLR4 inhibition using monoclonal antibodies from 20 patients with sepsis." (PMID 34733114, 2021). "HMGB1, another TLR4 ligand, is an important inflammatory mediator in lethal sepsis." (PMID 34360659, 2021). "RAGE-aptamer could break the crosstalk between HMGB1-RAGE axis and ROS, thereby improving the sepsis score and survival rate in LPS-injected septic mice." (PMID 34413930, 2021). "Moreover, NEAT1 was reported to enhance the immune response through activation of the high-mobility group box 1 (HMGB1)/receptors for advanced glycation end products (RAGE) and NF-κB pathway, which exacerbated lung epithelial cell injury in sepsis mice." (PMID 34630395, 2021).